CCL17 (C-C motif chemokine ligand 17)
Diseases named in the same sentence as CCL17 in open-access papers (continued):
Sharing a sentence is not in itself a finding about the gene and the disease.
hematoma (4 papers, 2021 to 2025). A hematoma is a collection of blood from a vascular structure into an extravascular space. "Our findings extend previous work by revealing that the CCL17/CCR4 axis enhances hematoma clearance through the ERK/AP1/SRA pathway‐mediated microglial polarization." (PMID 39996481, 2025). "This investigation extends our previous work on CCL17/CCR4‐mediated hematoma resolution and provides new insights into potential therapeutic strategies for ICH treatment." (PMID 39996481, 2025). "CCL17 therapy promotes early hematoma regression after intracerebral hemorrhage through the CCR4/ERK/Nrf2/CD163 pathway." (PMID 35959472, 2022). "In our previous study, we mainly focused on the exploration of therapeutic dose-response of CCL17 and its effect on hematoma clearance after ICH." (PMID 33648537, 2021). "The recombinant CCL17 (rCCL17) administration might promote hematoma resolution by increasing the expression of CD163 on microglia/macrophages, further reducing perihematomal edema and improving neurobehavior outcomes." (PMID 36704330, 2022). "In addition to the effects of CCL17 on hematoma resolution, the axis also could alleviate neuroinflammation and neuronal apoptosis via the CCR4/PI3K/AKT/Foxo1 signaling pathway at 72 h post-ICH." (PMID 36704330, 2022). "In conclusion, our findings suggest that the CCL17/CCR4 axis plays a pivotal role in microglial polarization and hematoma clearance after ICH, with potential therapeutic implications." (PMID 39996481, 2025). "The study identifies the critical role of the CCL17/CCR4 axis in microglial polarization and hematoma clearance following intracerebral hemorrhage." (PMID 39996481, 2025). "This study investigates how the CCL17/CCR4 signaling pathway modulates microglial phenotype transition and enhances hematoma resolution after ICH, building upon our earlier findings showing CCR4's involvement in neuroinflammatory responses." (PMID 39996481, 2025). "This study investigates the role of the CCL17/CCR4 axis in regulating microglial polarization and hematoma clearance following intracerebral hemorrhage (ICH), with a focus on the downstream ERK/AP1/SRA signaling pathway." (PMID 39996481, 2025). "Given the neuroprotective roles of CCL17, its activation has become a promising therapeutic approach for early therapy of ICH and contributing to hematoma absorption." (PMID 36704330, 2022). "Based on our preliminary data and published findings, we hypothesize that CCL17/CCR4 signaling modulates the ERK/AP1/SRA pathway to promote M2 polarization, thereby facilitating hematoma clearance and reducing secondary brain injury." (PMID 39996481, 2025). "To explore the therapeutic potential of rCCL17 in ICH, we administered recombinant CCL17 (rCCL17), a CCR4 ligand, intranasally to mice 1 h post‐ICH and evaluated its effects on neurological function, hematoma progression, brain edema, and microglial polarization." (PMID 39996481, 2025). "It has been reported that treatment with CCL17, a specific ligand of CCR4, promotes hematoma resolution through the CCR4/ERK/Nrf2/CD163 pathway, thereby, improving neurological function, which is associated with microglia-mediated erythrocyte phagocytosis and clearance of tissue debris." (PMID 35959472, 2022). "However, the specific mechanisms by which the CCL17/CCR4 axis regulates microglial polarization and hematoma clearance remain unclear." (PMID 39996481, 2025).
leukemia (4 papers, 2015 to 2024). A malignant (clonal) hematologic disorder, involving hematopoietic stem cells and characterized by the presence of primitive or atypical myeloid or lymphoid cells in the bone marrow and the blood. "Furthermore, the expression of most M2-associated genes, such as Arg1, CCL3, CCL17, CD206, IL-10, and TGF-β decreases with the infiltration of leukemia cells, whereas the expression of MMP9 and VEGFα increases in the advanced stages of leukemia." (PMID 38779660, 2024). "In particular, we focused our attention on its potential effect on CCL17, CD40 and PI3KCD mRNAs, which are biologically relevant to CLL, and on DDR1 mRNA that encodes a tyrosine kinase receptor expressed in several tumors and leukemias." (PMID 26305332, 2015). "It has been shown that Tregs strongly express CCR4, a chemokine receptor for CCL17 or CCL22, on their surface as compared to effector T cells in leukemia studies." (PMID 33816236, 2021). "Additionally, it has been demonstrated that primary leukemia cells secrete CCL22 and CCL17 in response to CD40 ligation, indicating that the chemokines may direct B-cell responses that are dependent on T lymphocytes in secondary lymphoid tissues by enlisting helper T lymphocytes and dendritic cells." (PMID 37259456, 2023).
pancreatic cancer (4 papers, 2020 to 2024). "It was recently shown that the CCL17-eluting scaffold prevents tumor progress in pancreatic cancer by attracting CCR4+CD4+ T cells." (PMID 37371612, 2023). "In a Pan02 pancreatic cancer mouse model, characterized by the secretion of the chemokines CCL17 and CCL22, the use of a CCR4 antagonist (CCR4-351) has shown significant effects in disrupting the CCR4-CCL17/CCL22 chemotactic axis, which effectively blocks the recruitment of Tregs to the TME." (PMID 38500876, 2024). "Notably, the keywords included T-cell differentiation, T-cell development, DNA methylation, histone modification, TH2 cell activation, CCL17 production, IL-18 secretion, and pancreatic cancer, all of which participate in either immune regulation or cancer." (PMID 33664764, 2020).
renal fibrosis (4 papers, 2020 to 2022). A final common manifestation of a wide variety of chronic kidney diseases characterized by glomerulosclerosis and tubulointerstitial fibrosis. "Further research is needed to gain an in-depth understanding of the mechanism underlying the promotion of renal fibrosis progression by CCL17." (PMID 34943853, 2021). "CCL17 induced renal fibrosis by promoting the epithelial-mesenchymal transition, resulting in ECM accumulation." (PMID 34943853, 2021). "CCL17, a chemotactic cytokine produced by macrophages, is known to promote inflammatory and fibrotic effects in multiple organs, but its role in mediating renal fibrosis is unclear." (PMID 34943853, 2021). "The precise molecular mechanisms of TGF-β1/Smad/MAPKs/NF-κB was a signaling pathway as a regulation for CCL17 expression in renal fibrosis in vitro and in vivo which is currently under investigation." (PMID 34943853, 2021). "Taken together, these data indicate that myofibroblast CD248 induced pro-fibrotic phenotype switching of macrophages through galectin-3, and that macrophage CCL17 upregulated collagen expression of myofibroblasts thereby leading to renal fibrosis." (PMID 33033277, 2020). "CD11b+/Ly6Clow M2 macrophages contribute to renal fibrosis by producing pro-fibrotic factors, including platelet-derived growth factor, insulin-like growth factor (IGF)-1, and CCL17, all of which are highly correlated with fibrogenesis or wound healing." (PMID 35990680, 2022). "In addition, the elevated secretion of pro-inflammatory cytokines, including M1-related CXCL1 and CXCL10 and M2-related CCL17 and CCL26, may augment in the early phase of renal inflammation and in the late phase of renal fibrosis in folic acid-induced RIF." (PMID 35990680, 2022). "The roles of CCL17 and CCL22 in the progression of renal fibrosis remain unclear." (PMID 34943853, 2021).
sarcoidosis (4 papers, 2013 to 2025). Sarcoidosis is a multisystemic disorder of unknown cause characterized by the formation of immune granulomas in involved organs. "CCL17 has also been shown to be involved in Th2-mediated cystic fibrosis, peritoneal fibrosis, and the granuloma formation of sarcoidosis." (PMID 35687056, 2022).
skin tumor (4 papers, 2018 to 2022). "In the present study, to elucidate the role of CCL17 in tumor immunity, skin tumors and lung metastasis were evaluated." (PMID 33670758, 2021). "In the present study, the frequency of CCR4+ cells in the skin tumor was increased in CCL17 TG mice as had been expected." (PMID 33670758, 2021). "Our study showed that CXCL17 expression was decreased in the skin tumor of CCL17 TG mice, while IL-4 expression was increased." (PMID 33670758, 2021). "CXCL17, CCR2, and CCL5 mRNA levels were significantly decreased in skin tumors of CCL17 TG mice compared with WT mice." (PMID 33670758, 2021). "CCL17 overexpression enhanced skin tumor formation and lung metastasis with concomitant increases in Tregs in the skin, lymph nodes, and spleen." (PMID 33670758, 2021). "The skin tumor microenvironment contained potentially tumor-permissive myeloid cells producing regulatory (IDO1) and Th2-associated mediators (CCL13, CCL17, CCL22)." (PMID 33968070, 2021). "In skin cancer, chemokines such as CCL-17 and CCL-18 secreted by stromal cells can recruit immunosuppressive regulatory T (Treg) cells to infiltrate in tumor islands, and overexpression of CCL-17 and its ligand CCR-4 can promote the aggregation of CD4-positive (CD4+) Treg, Th2 and Th17 cells." (PMID 36159822, 2022). "Interestingly, while Tregs were increased in the skin, lymph nodes, and spleen of CCL17 TG mice, MDSCs in the skin tumor were significantly decreased." (PMID 33670758, 2021). "As expected, the frequency of CCR4+ cells was increased in the skin tumors of CCL17 TG mice." (PMID 33670758, 2021).
type 1 diabetes (4 papers, 2014 to 2025). "The simultaneous upregulation of chemokines that promote (CXCL10, CXCL9) and protect against (CCL17, CCL22) type 1 diabetes suggests a complex immune response to PET microplastics." (PMID 40597598, 2025).
viral infection (4 papers, 2013 to 2024). "In turn, AECs of both humans and mice have been shown to be a major source of TARC/CCL17, the main chemoattractant for TH17 cells, in response to viral infection and/or stimulation with the TH2-type cytokine IL-4." (PMID 37759430, 2023).
coronary artery disease (3 papers, 2019 to 2023). "The T allele in CCL17(rs223828) was associated with increased serum CCL17 levels as well as increased coronary artery disease risk in a Chinese Han Population29." (PMID 37730733, 2023).
emphysema (3 papers, 2022 to 2024). "In this study, CCL-17 was significantly decreased in the emphysema group, whereas IL-13 and IL-4 were elevated." (PMID 36248880, 2022). "The reduction of CCL-17 suggests that the reduction of M2 macrophages in emphysema is mainly dominated by the M2a subtype, and the reduction of the M2a subtype in turn stimulates the increase of IL-13 and IL-4, and also leads to a decrease in anti-inflammatory capacity." (PMID 36248880, 2022). "The levels of inflammatory cytokines related to type 2 inflammation (including CCL11, CCL17, and CCL22) were significantly elevated in the emphysema model compared to the controls." (PMID 37816708, 2023).
eosinophilic disease (3 papers, 2023 to 2025). "Second, considering the increase of serum CCL17 levels due to eosinophilic disease, we excluded patients with eosinophilic disease or increased blood eosinophil counts from the validation cohort." (PMID 40269953, 2025). "CCL17 was also noted to be an important biomarker for eosinophilic disorders including differentiating eosinophilic pneumonia from acute lung injury." (PMID 36809921, 2023).
food allergy (3 papers, 2012 to 2022). Gastrointestinal disturbances, skin eruptions, or shock due to allergic reactions to allergens in food. "The reduction of CCL11 and CCL17 expression was also observed only in the ileum further providing support to this site being an “active” site of inflammation in a gastrointestinal food allergy immune response as well as a site of action of L. lactis NCC 2287." (PMID 21961022, 2012).
influenza (3 papers, 2014 to 2024). An acute viral infection of the respiratory tract, occurring in isolated cases, in epidemics, or in pandemics; it is caused by serologically different strains of viruses (influenzaviruses) designated A, B, and C, has a 3-day incubation period, and usually lasts for 3 to 10 days. "Although in influenza-infected mice, expression of CCL17 and CCL22 by airway epithelial cells is associated with imprinting of CCR4+CD4+ T cells by lung dendritic cells, our findings suggest that this does not occur with human RSV." (PMID 31815739, 2020).
intracerebral hemorrhage (3 papers, 2022 to 2025). A cerebrovascular disorder characterized by bleeding into one or both cerebral hemispheres including the basal ganglia and the cerebral cortex. "Our previous studies demonstrated that CCL17 and its receptor CCR4 play crucial roles in neuroinflammation and microglial activation following intracerebral hemorrhage (ICH)." (PMID 39996481, 2025).
leprosy (3 papers, 2014 to 2025). Leprosy is a chronic infectious disease affecting primarily the skin and peripheral nervous system. "Our study may be underpowered to determine a significant association between CCL18 and CCL17 serum levels and leprosy phenotype." (PMID 25412496, 2014). "The primary finding of our study is that dermal mRNA levels of CCL17 and CCL18, two chemokines important in the development of a TH2 T-cell response, are associated with tuberculoid and lepromatous leprosy respectively." (PMID 25412496, 2014). "In order to adjust for age we analyzed CCL17 and CCL18 associations with leprosy phenotype in patients born before 1966 (cutoff age of 45)." (PMID 25412496, 2014). "CCL17 and CCL18, were more strongly associated with leprosy polarity than traditional TH1 and TH2 cytokines." (PMID 25412496, 2014). "Our findings suggest that CCL17 and CCL18 dermal expression is associated with leprosy polarity." (PMID 25412496, 2014). "Together, these data suggest that both CCL17 and CCL18 dermal mRNA levels are associated with tuberculoid and lepromatous leprosy, respectively and are more strongly associated with polarity than common TH1/TH2 markers typically used to characterize leprosy lesions." (PMID 25412496, 2014). "CCR4 serves as the receptor for CCL17 and CCL22, the latter displaying the most prominent difference in this study between contacts and patients with leprosy, with unprecedented discriminatory potential for BT/TT patients and contacts." (PMID 40683203, 2025). "We found that three soluble mediators (CCL17, CCL18 and IL10) and one cell marker (CD14) were differentially expressed in leprosy dermal lesions." (PMID 25412496, 2014). "Herein we show that two chemokines, CCL17 and CCL18, more accurately define leprosy polarity than traditional TH1 and TH2 cytokines." (PMID 25412496, 2014). "Interestingly, our study demonstrated that CCL17 and CCL18 distinguished leprosy polarity with greater accuracy than the traditional TH1 and TH2 cytokines (IL10, IFNG)." (PMID 25412496, 2014). "Next the serum levels of CCL17 and CCL18 were compared in 6 EC (5 from Nepal and one from non-endemic area) patients without leprosy, versus 20 patients with leprosy (11 with BT, 2 with BL, and 7 with LL by RJ classification as determined by biopsy)." (PMID 25412496, 2014).
mycosis fungoides (3 papers, 2018 to 2021). Classical mycosis fungoides is the most common type of mycosis fungoides (MF), a form of cutaneous T-cell lymphoma, and is characterized by slow progression from patches to more infiltrated plaques and eventually to tumors. "In patients with CTCL [either mycosis fungoides (MF) or Sézary syndrome (SS)], serum concentrations of CCL11 and CCL17 were increased and correlated with disease activity." (PMID 34503058, 2021).
Myocardial fibrosis (3 papers, 2022 to 2026). "By deleting Ccl17, Treg migration into the myocardium improved, leading to lower myocardial fibrosis and improved cardiac function." (PMID 38093747, 2023). "Compared with IgG controls, CCL17 antibody-treated mice exhibited remarkable attenuation of the Ang II–induced cardiac dysfunction, increases in the myocyte area, and myocardial fibrosis." (PMID 35687056, 2022).
neuropathy (3 papers, 2020 to 2023). A disorder affecting the nervous system that manifests with pain, tingling, numbness, and/or muscle weakness. "Our biochemical studies were performed in rats exposed to CCI and revealed increased levels of CCL17 and CCL22 in the dorsal root ganglia during the development of neuropathy." (PMID 36555280, 2022). "Moreover, taking into consideration our results and aforesaid literature, all three chemokines acting via CCR4, that is, CCL17, CCL22, and CCL2, seem to be important mediators in pathological nociceptive processes at the DRG level under neuropathy." (PMID 32760393, 2020). "However, the levels of CCL17 and CCL22 in the spinal cords of rats and mice in this model were not changed in the early and late stages of neuropathy." (PMID 36555280, 2022).
non-small cell lung carcinoma (3 papers, 2022 to 2024). A group of at least three distinct histological types of lung cancer, including non-small cell squamous cell carcinoma, adenocarcinoma, and large cell carcinoma. "On the other hand, tumour-associated neutrophils can produce CCL17, recruiting CD4 T regulatory cells that promote immune evasion and cancer development in non-small cell lung cancer." (PMID 35226704, 2022).
T-cell lymphoma (3 papers, 2014 to 2018). "Previous studies have shown that CCL17/TARC induced chemotaxis of the mouse T-cell lymphoma cell line EL4 in a MEK1/2-ERK1/2-dependent manner." (PMID 30140381, 2018).
vitiligo (3 papers, 2021 to 2025). Generalized well circumscribed patches of leukoderma that are generally distributed over symmetric body locations and is due to autoimmune destruction of melanocytes. "The CCL17/CCR4 axis is also important for the onset of vitiligo in mice, and CCR4 neutralization reversed depigmentation in animals." (PMID 36555280, 2022). "CCR4 and CCL17 were highly expressed in the skins of patients with vitiligo." (PMID 36555280, 2022). "To investigate whether CCL17 is critical for depigmentation, we adoptively transferred CFP‐PMEL CD8+ T cells into wild type (WT) or CCL17‐deficient (CCL17−/−) KRT14‐Kitl*4XTG2Bjl (Krt14‐Kitl*) mice to induce vitiligo." (PMID 34077992, 2021). "In contrast to the findings in vitiligo, Th2 signaling was prominent as well, with consistent upregulation of CCL13, CCL17, CCL22, and CX3CL1." (PMID 40969764, 2025). "We initially examined CCL17 and CCR4 messenger RNA (mRNA) levels in skin samples from lesion area and its surrounding normal areas of 30 vitiligo patients." (PMID 34077992, 2021). "In conclusion, our results demonstrated the high expression of CCL17, CCR4 and the elevated activation of CD8+ T cells in skin lesions of vitiligo patients." (PMID 34077992, 2021). "This article aims to identify the role of CC chemokine ligand 17 (CCL17)–CC chemokine receptor 4 (CCR4) axis in vitiligo and provide new possibilities for the clinical treatment of vitiligo." (PMID 34077992, 2021). "In this paper, we examined the expression of CCL17 and CCR4 in the lesion area and its surrounding normal areas of vitiligo 30 patients." (PMID 34077992, 2021). "Here, we reported that the elevated expression of CCL17 and CCR4 is essential for the progression of vitiligo utilizing a mouse model." (PMID 34077992, 2021).
allergic contact dermatitis (2 papers, 2018 to 2021). An inflammatory skin condition caused by an immune response to direct contact between the skin and an allergen. "Moreover, using a mouse model for human allergic contact dermatitis, it was shown that IL-17 deficiency decreases CCL17 expression." (PMID 29931394, 2018).
autoimmune disorders (2 papers, 2017 to 2021). "The aim of this review is to highlight the involvement of a C-C class chemokine/receptor axis, consisting of C-C chemokine ligands 17 (CCL17) and 22 (CCL22), and C-C chemokine receptor 4 (CCR4), in CNS autoimmunity." (PMID 29099057, 2017).
B cell lymphoma (2 papers, 2018 to 2023). "An enhanced expression of CCL17/TARC has been reported in several human malignancies, such as Hodgkin’s and B cell lymphoma." (PMID 30140381, 2018).